PRSS1 (serine protease 1)
Diseases named in the same sentence as PRSS1 in open-access papers (continued):
Sharing a sentence is not in itself a finding about the gene and the disease.
chronic pancreatitis (46 papers, 2007 to 2025). A chronic inflammatory process causing damage and fibrosis of the pancreatic parenchyma. "Eighty percent of family members with HCP have recurrent acute pancreatitis leading to chronic pancreatitis due to mutations in the cationic trypsinogen (PRSS1) gene." (PMID 40944111, 2025). "Pathogenic mutations in PRSS1 are associated with an over 80% chance of recurrent acute and/or chronic pancreatitis, as well as an exceptionally high lifetime risk of pancreatic ductal adenocarcinoma (estimated at 40%)." (PMID 39896151, 2024). "The aim of the study was to determine the structure of chronic pancreatitis genetic causes in patients living in the European part of Russia by sequencing the entire coding sequence of the PRSS1, SPINK1, CTRC, CFTR, and CPA1 genes." (PMID 37389024, 2023). "PVs in two genes that are associated with AD chronic pancreatitis-PRSS1 (OMIM #276000; PV-rs111033565) and CTRC (OMIM #601405; PV-rs202058123) were detected." (PMID 37107695, 2023). "Germline mutations in PRSS1 were associated with familial forms of chronic pancreatitis and extreme risk of PDAC." (PMID 35205822, 2022). "In the Genetic Risk Factors in Chronic Pancreatitis Database, variants in the PRSS1 and SPINK1 genes are systematically classified in accordance with the ACMG recommended five categories with the addition of a new “protective” category." (PMID 35974416, 2022). "PRSS1 aka trypsin/trypsinogen mutations increase risk of chronic pancreatitis and pancreatic cancer and its pathological activation promotes neoplasia." (PMID 33334063, 2020). "Here we report the novel PRSS1 c.568G>A (p.Glu190Lys) mutation identified in a case of chronic pancreatitis." (PMID 30792736, 2019). "Previous studies revealed somatic mutations of the cationic trypsinogen gene (PRSS1) in patients with chronic pancreatitis and pancreatic cancer." (PMID 31521106, 2019). "As a case in point, here we present the rare p.Glu190Lys missense variant in the PRSS1 gene identified in a Polish subject with chronic pancreatitis." (PMID 30792736, 2019). "Among subjects with chronic pancreatitis, the risk of pancreatic cancer increases with increasing duration of pancreatitis and is highest among those with young-onset recurrent acute/chronic pancreatitis as is seen in patients with inherited PRSS1 mutations." (PMID 28881607, 2017). "According to previous studies, PRSS1 gene mutations are considered a typical feature for hereditary chronic pancreatitis." (PMID 28348582, 2017). "In chronic pancreatitis mutations of the cationic trypsinogen (PRSS1) gene have been identified as risk factors of the disease." (PMID 24600409, 2014). "Mutations in the PRSS1 gene, encoding cationic trypsinogen, play a causative role in chronic pancreatitis." (PMID 17204147, 2007). "The c.311T > C (p.L104P) pathogenic variant of the serine protease 1 (PRSS1) gene (encoding cationic trypsinogen) is frequently found in families with hereditary chronic pancreatitis (HCP), often presents as recurrent acute pancreatitis and serves as precursor to CP." (PMID 40401174, 2025). "This case report describes a 24-year-old man with a history of hereditary chronic pancreatitis resulting from a serine protease 1 (PRSS1) gene pathogenic variant, who presented with fasting hyperglycemia and elevated glycated hemoglobin requiring early insulin therapy." (PMID 40401174, 2025). "His mother has chronic pancreatitis and PRSS1 mutation diagnosed in adulthood." (PMID 38978842, 2024). "His uncle was diagnosed with chronic pancreatitis and PRSS1 gene mutation." (PMID 38978842, 2024). "Consequently, heterozygous CPA1 and PRSS1 misfolding mutations are considered as strong risk factors, and are solely capable of inducing chronic pancreatitis." (PMID 35704637, 2022).
chronic pancreatitis (continued). "Bertin has recently shown that mutations in the cystic fibrosis transmembrane conductance regulator gene (CFTR), the serine protease inhibitor Kazal type 1 gene (SPINK1), and the cationic trypsinogen gene (PRSS1) are associated with both chronic pancreatitis and acute recurrent pancreatitis." (PMID 33319053, 2020). "Other commonly identified genes whose mutations are associated with chronic pancreatitis include the cationic trypsinogen gene (PRSS1) and Cystic Fibrosis Transmembrane Conductance Regulator gene (CFTR), with the later gene being the most common genetic variant to co-exist with SPINK1 mutations." (PMID 29515728, 2017). "Interestingly PRSS1 5’UTR SNPs are known to be associated with chronic pancreatitis." (PMID 33256598, 2020). "Mutations in the genes encoding cationic trypsinogen (PRSS1) determine an increased susceptibility to acute and chronic pancreatitis by making molecules more susceptible to activation." (PMID 39757373, 2025). "Genes, such as CFTR, PRSS1, and SPINK1, are involved in trypsinogen activation and regulation, with mutations contributing to recurrent acute episodes and progression to chronic pancreatitis." (PMID 39595191, 2024). "Inherited gene variants that impose risk (in genes including PRSS1, SPINK, CTRC, CFTR, and CPA1) typically result in premature activation of digestive enzymes in acinar cells, and have been linked to chronic pancreatitis." (PMID 37452870, 2023). "Inherited risk factors include gene variants damaging in PRSS1 and CFTR (both also associated with chronic pancreatitis), and tumor suppressors involved in DNA repair processes (including BRCA1, BRCA2, PALB2, MLH1, CDKN2A, and ATM)." (PMID 37452870, 2023). "Recurrent variants of the PRSS1, SPINK1, CTRC, CFTR, and CPA1 genes, contributing to the genetic predisposition to chronic pancreatitis development were identified in a cohort of Russian patients." (PMID 37389024, 2023). "Another proteomic study found that the expression of PRSS1 in pancreatic acinus of mice with chronic pancreatitis was also significantly altered." (PMID 35745003, 2022). "For reported variants in the PRSS1, SPINK1 and CTRC genes, the reader is referred to the Genetic Risk Factors in Chronic Pancreatitis Database." (PMID 35974416, 2022). "Of the 25 patients, 18 (72%) of them were found to have a known genetic mutation (PRSS1, SPINK1, CFTR, CTRC) as the etiology for acute recurrent or chronic pancreatitis." (PMID 33925523, 2021). "Rare pathogenic variants in the SPINK1, PRSS1, CTRC, and CFTR genes have been strongly associated with a risk of developing chronic pancreatitis (CP)." (PMID 30420730, 2018). "Mutations in genes encoding cationic trypsinogen (PRSS1), pancreatic secretory trypsin inhibitor (SPINK1) and chymotrypsinogen C (CTRC) are associated with chronic pancreatitis." (PMID 24260417, 2013). "Mutations in the PRSS1 and SPINK1 genes are recognized as important risk factors for chronic pancreatitis (CP); however, their clinical relevance in Vietnamese populations remains unclear." (PMID 40979245, 2025). "In addition to HCP, a number of genetic variations, in order of decreasing risk effect in the PRSS1, CPA1, SPINK1, CTRC, CEL and CFTR genes, have been found to raise the risk of developing chronic pancreatitis, particularly when other risk factors are present." (PMID 40944111, 2025). "The developed genetic panel (PRSS1, SPINK1, CTRC, CFTR, and CPA1 genes) for identification of genetic risk factors of the chronic pancreatitis development and the usage of the next-generation sequencing technology allowed to specify genetic predictors of the disease development in 61% of patients." (PMID 37389024, 2023). "Missense mutations in pancreatic secretory enzymes such as CPA1, PRSS1, CEL and PNLIP may lead to protein misfolding and the development of ER stress, which may predispose to chronic pancreatitis." (PMID 35704637, 2022).
chronic pancreatitis (continued). "It is important to note, however, that investigation of the PRSS1 gene in patients with suspected genetically determined chronic pancreatitis is restricted to these exons in most laboratories and possible C-terminal mutations may have been missed." (PMID 17204147, 2007). "Although PRSS1 and CPA1 variants have been linked to pancreatic cancer risk, to date variants in other chronic pancreatitis susceptibility genes such as SPINK1 and CFTR have not been consistently found to be risk factors for pancreatic cancer." (PMID 28881607, 2017). "Given that in the pancreas, PRSS1, SPINK1 and CTRC are expressed exclusively in the acinar cells, these genetic findings suggested an important role for prematurely activated trypsinogen within the pancreatic acini in initiating chronic pancreatitis." (PMID 23951356, 2013).
pancreatic cancer (39 papers, 2007 to 2025). "In particular, STK11 and PRSS1 are associated with an especially high risk of developing pancreatic cancer, but variants in these genes are very rare." (PMID 38961426, 2024). "According to international guidelines, patients with CP accompanied by serine protease 1 gene (PRSS1) mutation are recommended to undergo regular follow-up for pancreatic cancer detection." (PMID 36596818, 2023). "For PRSS1, such mutation pattern has only been found in pancreatic cancer, validating our prediction." (PMID 34513841, 2021). "It is well known that CP patients with PRSS1 or SPINK1 gene mutations belong to a high-risk group for pancreatic cancer, with an estimated risk 53–87 times higher than the normal population." (PMID 33375361, 2020). "PRSS1 mutations can increase the risk of pancreatic cancer and are closely related to susceptibility to gastric cancer." (PMID 33585454, 2020). "In our previous study, PRSS1 gene mutations were detected in peripheral blood samples from pancreatic cancer patients; in addition, trypsin is a pancreas specific enzyme." (PMID 31521106, 2019). "This study uncovered increased serum trypsin levels and PRSS1 mutation in pancreatic cancer patients, and the gene variation was in somatic cells." (PMID 31521106, 2019). "In our previous study, the PRSS1 mutations p.T135A, p.T137 M, and p.C139S were detected in pancreatic cancer patients, with the PRSS1_rs10273639 genotype impacting the clinical outcome of this malignancy." (PMID 31521106, 2019). "This review will mainly focus on the question if pancreatic cancer is especially frequent in those patients that are predisposed to CP by the presence of a PRSS1 mutation." (PMID 24600409, 2014). "Taken together, the pancreatic cancer risk in HCP patients with a PRSS1 mutation seems to be elevated – with an uncertain relative risk increase." (PMID 17204147, 2007). "Obviously, the data basis for the estimation of the pancreatic cancer risk in patients with PRSS1 associated HCP is small." (PMID 17204147, 2007). "For example, whether PRSS1 mutations detected in peripheral blood samples from pancreatic cancer patients are causal factors of pancreatic carcinogenesis is unclear." (PMID 31521106, 2019). "In addition, it remains unknown whether PRSS1 mutations enhance malignant proliferation and invasion in pancreatic cancer." (PMID 31521106, 2019). "This could be the etiology of pancreatic cancer caused by PRSS1 mutation." (PMID 31521106, 2019). "However, whether PRSS1 mutations trigger pancreatic cancer and/or promote malignant proliferation and metastasis in pancreatic cancer remains largely unclear, as well as the potential underlying mechanisms." (PMID 31521106, 2019). "This is exemplified in individuals with cystic fibrosis and patients with hereditary pancreatitis due to mutations in PRSS1 or SPINK1, who have an increased risk of pancreatic cancer due to chronic inflammation and related changes in the pancreas." (PMID 38539517, 2024). "The lifetime risk of pancreatic cancer is highest for patients with known germline variants in three unique genes: STK11, CDK2NA, and PRSS1." (PMID 37165697, 2023). "Tier I or II mutations related to hereditary cancer syndrome in pancreatic cancer were identified in BRCA1 (n = 2, 2.3%), BRCA2 (n = 2, 2.3%), PRSS1 (n = 1, 1.1%), MSH6 (n = 2, 2.3%), PMS2 (n = 1, 1.1%), and APC (n = 1, 1.1%)." (PMID 36463295, 2022). "Over the last decade, the genetics associated with pancreatic cancer has been intricately assessed Some well-known cancer gene germline mutations have been identified in patients with pancreatic cancer, including BRCA1/2, PALB2, STK11, PRSS1, SPINK1 and ATM." (PMID 35813042, 2022).
pancreatic cancer (continued). "KLHDC7B, CASP14, and PRSS1 are putatively oncogenic gene that has been demonstrated in breast cancer and pancreatic cancer, and the role of KLHDC7B was correlated with extracellular communication, cell morphology, gene expression, and actin binding." (PMID 33987102, 2021). "Among them, the most distinguished is the cationic trypsinogen gene (PRSS1), even though it is responsible only for a small portion of pancreatic cancer cases." (PMID 31521106, 2019). "Compared with CP tissues (harboring wild type PRSS1), ERK and VEGFR2 expression levels were obviously higher in pancreatic cancer tissues carrying the PRSS1_R116C mutation." (PMID 31521106, 2019). "Recent studies have shown that the expression of PRSS1 protein is significantly increased in pancreatic cancer, colorectal cancer and cervical cancer and may be involved in the pathological process of tumor progression 7-9." (PMID 33867821, 2021). "To assess whether the PRSS1_R116C mutation itself enhances malignant behaviors in pancreatic cancer or triggers the latter by increasing trypsin levels, we constructed stable PANC-1 cell lines with overexpression of PRSS1_R116C (R116C) or wildtype PRSS1 (OE)." (PMID 31521106, 2019). "RT-qPCR and confocal microscopy demonstrated at the RNA and protein levels, respectively, that PAR-2 was significantly upregulated in pancreatic cancer cells with PRSS1_R116C or with PRSS1 overexpression, and both molecules colocalized in both tissues and cells." (PMID 31521106, 2019). "Mutations in the high penetrance genes such as BRCA2, PALB2, p16/CDKN2A, PRSS1, SPINK1, and STK11 correlate with a very high lifetime risk of developing pancreatic cancer and may cause as many as 10% of pancreatic cancers in the US." (PMID 24883056, 2014). "The authors claim that the clinical features were not influenced by the presence of a gene mutation except for an earlier age at onset and a higher incidence of pancreatic cancer, especially in patients with a CFTR mutation (four cancer patients had CFTR mutations, one a PRSS1 mutation)." (PMID 24600409, 2014). "Pancreatic cancer was diagnosed in 26 (6%) patients and arose in individuals carrying any of the common mutations as well as in PRSS1-mutation negative families (14x R122H, 7x N29I, 1x A16V and 4x no PRSS1 mutation)." (PMID 24600409, 2014). "PRSS1 mutations were present in 68% (78% R122H, 12% N29I, 10% others) of the study cohort and again the PRSS1 mutation type did not correlate with the development of pancreatic cancer, which was diagnosed in ten individuals at a median age of 55." (PMID 24600409, 2014). "Therefore, further analyses are needed to clarify the role of the CTRB1-CTRB2 locus in pancreatic cancer risk, which could include pre-clinical assessment of CTRB1 and CTRB2 as potential anti-tumour agents as was previously conducted for pro-enzymes PRSS1 and Chymotrypsinogen A28." (PMID 38684708, 2024). "A European study revealed a mean age of onset of 10 years and 14.5 years for affected carriers of the PRSS1 mutations R122H and N29I, respectively, but showed no mutation-dependent differences in complications such as exocrine or endocrine insufficiency or increased pancreatic cancer risk." (PMID 17204147, 2007). "We show that germline testing detects a PV in 23.9% of subjects with AP or CP, including PRSS1 (4.5%) and biallelic CFTR (1.3%) which have direct implications for management (pancreatic cancer screening and cascade testing for PRSS1, testing for cystic fibrosis for biallelic CFTR)." (PMID 39172977, 2024). "Interestingly, we found that PRSS1 is negatively expressed in PDAC, although it has often been related to pancreatic cancer." (PMID 32197468, 2020).
acute pancreatitis (12 papers, 2011 to 2025). An acute inflammatory process that leads to necrosis of the pancreatic parenchyma. "In the present study, we describe a rare case of HP with a PRSS1 mutation diagnosed based on the identification of multiple pseudocysts during the first acute pancreatitis-like episode." (PMID 39677196, 2024). "PRSS1-related hereditary pancreatitis is characterized by episodes of acute pancreatitis and recurrent acute pancreatitis with frequent progression to CP, which damages acinar cells through several mechanisms including oxidative stress and impaired autophagy." (PMID 35734414, 2022). "In addition, the increase in ATF6 expression was related to the increase of apoptosis, ER, and mitochondrial diseases in pancreatic tissues of patients with acute pancreatitis and PRSS1 mice." (PMID 38896161, 2024).